G0S2 (G0/G1 switch 2)
Diseases named in the same sentence as G0S2 in open-access papers (continued):
Sharing a sentence is not in itself a finding about the gene and the disease.
glioma (continued). "In comparisons between G-CIMP-positive tumors and G-CIMP-negative tumors, G0/G1 switch 2 (G0S2) exhibits the strongest differential expression, yet the mechanism and function of G0S2 in glioma are unclear." (PMID 30388142, 2018). "G0S2 mRNA expression was higher in the same human high-grade glioma tissues (secondary GBM) than in low-grade glioma tissues (diffuse astrocytoma; DA)." (PMID 30388142, 2018). "We also demonstrated that the expression of G0S2 was higher in post-operative recurrence diagnosed as WHO grade IV secondary GBM compared with initial glioma diagnosed as WHO grade II diffuse astrocytoma in the same patient." (PMID 30388142, 2018). "G0S2 levels were significantly higher for wild-type IDH1 than for mutant IDH1 among WHO grade III/IV gliomas." (PMID 30388142, 2018). "Using the Cancer Genome Atlas (TCGA) database, we found that G0S2 expression elevated as the WHO grade increased among WHO grade II–IV gliomas." (PMID 30388142, 2018). "We demonstrated that glioma harboring mutant IDH1 epigenetically represses G0S2 expression, thereby suppressing surrounding cell invasion and resulting in a better prognosis." (PMID 30388142, 2018). "G0S2 gene expression was negatively associated with G0S2 methylation (Pearson’s r = -0.7719, Spearman’s rho = -0.6932) within WHO grade II–IV gliomas." (PMID 30388142, 2018). "Our in vitro experiments indicated that the downregulation of G0S2 expression can efficiently attenuate the invasion of glioma cells." (PMID 30388142, 2018). "If a patient is diagnosed WHO grade II/III low-grade glioma, specifically suppressing G0S2 methylation has the potential to prevent malignant transformation." (PMID 30388142, 2018). "Functional analysis identified G0S2 as a key metabolic regulator highly expressed in gliomas." (PMID 40519301, 2025). "Our findings provide deeper insight into metabolic reprogramming in gliomas and suggest that G0S2 may serve as a potential therapeutic target." (PMID 40519301, 2025). "Finally, we knocked out G0S2 in glioma cells and performed RNA sequencing to investigate differentially activated pathways." (PMID 40519301, 2025). "In summary, our results demonstrate a previously unknown function of G0S2 in enhancing glioma radioresistance through regulation of 53BP1 protein stability, which is related with G0S2 lipolytic inhibitor function." (PMID 30953555, 2019). "Here in this study, we show that G0S2 promotes tumor growth in gliomas." (PMID 30953555, 2019). "Since G0S2 is upregulated in radioresistant GSCs, we determined whether G0S2 is involved in glioma radiation resistance." (PMID 30953555, 2019). "Our results suggest that G0S2 mediates glioma radioresistance through 53BP1-regulated DNA repair." (PMID 30953555, 2019). "We firstly examined G0S2 expression in glioma cells and clinical specimens." (PMID 30953555, 2019). "Based on our results above, we hypothesized that G0S2 enhances radiation resistance of gliomas through regulation of Rad51 or 53BP1." (PMID 30953555, 2019). "Here, we show that G0S2 modulates radiation responses of gliomas." (PMID 30953555, 2019). "Acumulated data have indicated that G0S2 is also involved in cancer, including glioma." (PMID 30953555, 2019). "We then assessed expression of G0S2 in glioma cells and clinical specimens of patients." (PMID 30953555, 2019). "In contrast, overexpression of G0S2 promoted glioma cell radiation resistance." (PMID 30953555, 2019). "Conversely, overexpression of G0S2 promoted tumor growth in orthotopic glioma models." (PMID 30953555, 2019). "In addition, the lower G0S2 expression group clearly showed better over survival than the higher G0S2 expression group for all WHO grade II–IV gliomas (p = 1.181e-8) and for WHO grade II/III lower grade gliomas (p = 0.01371)." (PMID 30388142, 2018). "In addition, the stereotactic delivery of glioma cells with decreased G0S2 expression in the mouse brain resulted in prolonged survival." (PMID 30388142, 2018).
glioma (continued). "It should be noted that there may be a contamination of normal brain parenchyma when using surgical material from low grade gliomas, resulting in lower relative G0S2 expression levels in the samples we examined." (PMID 30388142, 2018). "Next, we analyzed the role of G0S2 in glioma invasion by a transwell assay." (PMID 30388142, 2018). "We hypothesize that G0S2 also regulates glioma radiation response through activation of DNA repair." (PMID 30953555, 2019). "Finally, we determined the mechanism by which G0S2 enhances radioresistance in gliomas." (PMID 30953555, 2019). "Interestingly, G0S2 mutations were not reported in 1102 gliomas among TCGA WHO grade II–IV gliomas, supporting the notion that G0S2 is epigenetically silenced in gliomas harboring IDH1 mutations." (PMID 30388142, 2018). "We downloaded the GSE67089 dataset and examined G0S2 mRNA expression in proneural (PN), mesenchymal (MES) subtyped GSCs, astrocytes, 16WF neural stem cells (NSCs) and five established glioma cell lines." (PMID 30953555, 2019). "Our findings uncover a new function for lipolytic inhibitor G0S2 as an important regulator for GSC radioresistance, suggesting G0S2 as a potential therapeutic target for treating gliomas." (PMID 30953555, 2019). "In contrast, compared with the controls, overexpression of G0S2 in glioma LN229 and U87 glioma cells significantly prevented IR-induced γ-H2AX foci formation in these cells." (PMID 30953555, 2019). "Further, mRNA expression of G0S2 was higher in recurrent malignant glioma, diagnosed as WHO grade IV secondary GBM, than in initial glioma, diagnosed as WHO grade II diffuse astrocytoma, within the same patient." (PMID 30388142, 2018). "Relative G0S2 expression was higher in GBM than in lower grade gliomas (7.57 vs. 3.59, p = 1269e-16), and was higher in WHO grade III glioma than in WHO grade II glioma (3.12 vs. 2.49, p = 0.006330) among the lower grade gliomas." (PMID 30388142, 2018). "We found that G0S2 expression tended to increase as the WHO grade increased, and G0S2 knockdown inhibited glioma invasion." (PMID 30388142, 2018). "According to our analysis, survival was longer for the lower G0S2 expression group than for the higher G0S2 expression group among the patients with WHO grade II–IV gliomas and WHO grade II/III gliomas in the TCGA dataset." (PMID 30388142, 2018). "Mutant IDH1 was statistically significantly related to both higher G0S2 methylation (0.749 vs. 0.366, p = 9.439e-53) and lower G0S2 expression (3.1 vs. 7.03, p = 0.000) compared to wild-type IDH1 among WHO grade II–IV gliomas." (PMID 30388142, 2018).
non-small cell lung carcinoma (3 papers, 2015 to 2020). A group of at least three distinct histological types of lung cancer, including non-small cell squamous cell carcinoma, adenocarcinoma, and large cell carcinoma. "Consistent with our results, G0S2 expression was down-regulated epigenetically by DNA hypermethylation in non-small cell lung cancer cell lines." (PMID 30388142, 2018). "Here we show that ectopic expression of G0S2 in non-small cell lung carcinomas (NSCL) inhibits triglyceride catabolism and results in lower cell growth." (PMID 26318046, 2015). "Lipid catabolism is regulated by G0S2 through interaction and inhibition of the Adipose Triglyceride Lipase (ATGL) and upregulation of G0S2 or downregulation of ATGL in non-small cell lung carcinomas stalls triglyceride catabolism and represses cell growth." (PMID 33175867, 2020).
pancreatic cancer (3 papers, 2021 to 2024). "In our endeavor, we confirmed that UTX promoted the expression of G0S2 by reducing the H3K27me3 modification level of its promoter, while this function could be significantly impaired by mutation on its JmjC domain in pancreatic cancer cells." (PMID 39707168, 2024). "More importantly, our results further verified that the malignant phenotype of pancreatic cancer was inhibited by overexpressed G0S2." (PMID 39707168, 2024). "The mystery of G0S2’s role in pancreatic cancer has yet to be solved." (PMID 39707168, 2024). "At present, only one study on the bioinformatics analysis of 179 pancreatic cancer samples and 171 normal pancreatic tissue samples on the GEPIA platform revealed that G0S2 was identified as a lipid drop-related factor and was differentially expressed in PC samples." (PMID 39707168, 2024).
acute promyelocytic leukemia (2 papers, 2013 to 2015). An aggressive form of acute myeloid leukemia (AML), characterized by arrest of leukocyte differentiation at the promyelocyte stage, due to a specific chromosomal translocation t(15;17) in myeloid cells. "The G0/G1 switch gene 2 (G0S2) is rapidly induced by all-trans-retinoic acid (RA)-treatment of acute promyelocytic leukemia (APL) and other cells." (PMID 23546556, 2013). "G0S2 is strongly induced in acute promyelocytic leukemia (APL) cells in response to all trans retinoic acid (ATRA) and we show that inhibition of ATGL in these cells by G0S2 is required for efficacy of ATRA treatment." (PMID 26318046, 2015). "A previous study has shown that G0S2 mRNA and protein is strongly induced in response to treatment with all-trans retinoic acid (ATRA) in Acute Promyelocytic Leukemia (APL) cells." (PMID 26318046, 2015).
chronic kidney disease (2 papers, 2022 to 2025). Impairment of the renal function secondary to chronic kidney damage persisting for three or more months. "Recently, one study has reported that the G0/G1 switch protein 2 (G0S2) mediated the production of renal inflammation in chronic kidney disease (CKD)." (PMID 35136032, 2022). "While G0S2 inhibitors are currently being explored in chronic kidney disease, their potential applications in oncology remain unclear." (PMID 40519301, 2025).
chronic myeloid leukaemia (2 papers, 2019 to 2022). "In a chronic myeloid leukemia cell line, K562, G0S2 gene was found to be silenced by gene methylation, and upregulation of G0S2 expression by retroviral transduction or treatment with 5-azacytidine inhibited the proliferation of K562 cells both in vitro and in a xenograft model." (PMID 30953555, 2019).
colon cancer (2 papers, 2013 to 2019). "The G0S2 gene is a simple example with only one VDR binding site within its chromosomal domain, which is used in all published VDR ChIP-seq data sets besides that from colon cancer cells." (PMID 24202443, 2013). "G0S2 was found epigenetically silenced in lung cancer and breast cancer lines, and engineered expression of G0S2 induced cell apoptosis through G0S2 binding to and antagonizing Bcl-2 in a lung and a colon cancer cell line but not in breast cancer cell lines." (PMID 30953555, 2019).
diabetes (2 papers, 2014 to 2023). "These previous studies suggested that G0S2 is critical for the regulation of physiological and pathological processes of NAFLD and diabetes." (PMID 37033250, 2023). "In patients with type 2 diabetes mellitus on insulin treatment, ATGL protein was borderline increased in subcutaneous adipose tissue, and G0S2 mRNA and protein were decreased when insulin treatment was withheld and patients were hyperglycaemic." (PMID 25118138, 2014). "The upregulation of PPAR-γ may highlight a new mechanism by which G0S2 helps improve insulin sensitivity in NAFLD and diabetes." (PMID 37033250, 2023). "However, the mechanisms of G0S2 regulated NAFLD and diabetes is still not clearly known." (PMID 37033250, 2023).
gastric cancer (2 papers, 2021 to 2023). A primary or metastatic malignant neoplasm involving the stomach. "Taken together, our findings demonstrated that circSNTB2 plays an essential role in gastric cancer by regulating miR-6938-5p through G0S2 and PDCD4 genes." (PMID 36366842, 2023). "Our findings highlighted that the expression of both G0S2 and PDCD4 were inhibited in gastric cancer tissues while compared with the normal tissues." (PMID 36366842, 2023). "Our research characterized the regulation of circSNTB2/miR-6938-5p/G0S2 and PDCD4 pathways and their role in gastric cancer." (PMID 36366842, 2023).
leukemia (2 papers, 2022 to 2025). A malignant (clonal) hematologic disorder, involving hematopoietic stem cells and characterized by the presence of primitive or atypical myeloid or lymphoid cells in the bone marrow and the blood. "Prior investigations have suggested that G0S2 helps maintain the quiescent state of cells by suppressing cell proliferation in human leukemia cells and hematopoietic stem cells." (PMID 40218345, 2025).
liposarcoma (2 papers, 2017 to 2022). A usually painless malignant tumor that arises from adipose tissue. "In contrast, double knockout of Pnpla2 and Lipe induced liposarcoma in mice, and abnormal expression of G0S2 was observed in double knockout liposarcoma tissues." (PMID 35912266, 2022). "Similar changes of GPNMB and G0S2 expression were present in a human liposarcoma database." (PMID 28459858, 2017). "Among these genes, the two with the greatest up- and down-regulation in liposarcoma were glycoprotein nonmetastatic melanoma protein B (Gpnmb) and G0–G1 switch gene 2 (G0S2), respectively." (PMID 28459858, 2017). "G0S2, the endogenous inhibitor of ATGL, is epigenetically methylated in several cancers, has been considered to function as a tumor suppressor and is markedly down-regulated in DAKO adipose tissue and DAKO liposarcoma." (PMID 28459858, 2017).
lymphoma (2 papers, 2012 to 2019). A malignant (clonal) proliferation of B- lymphocytes or T- lymphocytes which involves the lymph nodes, bone marrow and/or extranodal sites. "To identify G0S2-interacting proteins in hematopoietic cells, we transduced murine lymphoma EL4 cells with the V5-tagged G0S2 retrovirus because the scarce number of HSCs precluded a proteomic approach." (PMID 22693613, 2012).
myasthenia gravis (2 papers, 2020 to 2025). Myasthenia gravis (MG) is a rare, clinically heterogeneous, autoimmune disorder of the neuromuscular junction characterized by fatigable weakness of voluntary muscles. "In myasthenia gravis (MG), tacrolimus, an immunosuppressant, reduces NFAT5 and G0S2 expression in PBMCs, providing insights into both disease mechanisms and tacrolimus' mode of action." (PMID 40421201, 2025).
renal fibrosis (2 papers, 2022 to 2024). A final common manifestation of a wide variety of chronic kidney diseases characterized by glomerulosclerosis and tubulointerstitial fibrosis. "In vivo, MBD2 LysMcre attenuated unilateral ureteral obstruction (UUO) and ischemia/reperfusion (I/R)-induced renal fibrosis via downregulation of G0S2, which was demonstrated by the downregulation of fibronectin (FN), collagen I and IV, α-SMA, G0S2." (PMID 35136032, 2022). "We also discovered the molecular mechanism underlying MBD2-induced renal fibrosis in UUO and ischemic injury via upregulation of the expression of G0S2." (PMID 35136032, 2022). "In addition, the overexpression of G0S2 can promote the transition of M2 macrophages to M1 macrophages, exacerbating inflammation progression in the kidney and accelerating renal fibrosis." (PMID 38867262, 2024). "We hypothesized that MBD2 in macrophages might promote the differentiation of resting M0 macrophages to mediate the renal fibrosis by upregulating the expression of G0S2." (PMID 35136032, 2022).
rheumatoid arthritis (2 papers, 2013 to 2015). A chronic, systemic autoimmune disorder characterized by inflammation in the synovial membranes and articular surfaces. "Another gene previously showing a differential expression profile predictive of response to IFX is G0S2 (G0/G1 switch 2), involved in lymphocyte cell cycle regulation and found upregulated in rheumatoid arthritis and psoriasis." (PMID 26339133, 2015). "G0S2 is also upregulated in peripheral blood or bone marrow-derived mononuclear cells isolated from patients with different autoimmune diseases, including psoriasis, rheumatoid arthritis, vasculitis and lupus." (PMID 23546556, 2013).
squamous cell lung carcinoma (2 papers, 2017 to 2022). A carcinoma arising from squamous bronchial epithelial cells. "Interestingly another study reported that 5-Aza-2′-deoxycytidine, an inhibitor of DNA methylation, restored the G0S2 expression in squamous cell lung cancer cell lines, which suggested that DNA methylation might regulate G0S2 expression." (PMID 35136032, 2022). "Several studies have shown that G0S2 is methylated in vivo in head and neck squamous cell carcinoma (SCC) and squamous cell lung cancer." (PMID 29073263, 2017). "Previous studies showed that G0S2 is methylated in head and neck SCC and in squamous cell lung cancer." (PMID 29073263, 2017).
abdominal aortic aneurysm (1 paper, 2024). Enlargement and ballooning of the vessel that supplies arterial blood to the abdomen, pelvis and legs. "We obtained six macrophage hub genes (IL-1B, CXCL1, SOCS3, SLC2A3, G0S2, and CCL3) that can effectively diagnose abdominal aortic aneurysm." (PMID 38867262, 2024).
adenoma (1 paper, 2018). A neoplasm arising from the epithelium. "Two more genes had increased expression in carcinoma compared to adenoma, and these are FADS1 and G0S2." (PMID 30175151, 2018).
asthma (1 paper, 2022). "There is no clear conclusion regarding the functions of G0S2 in asthma." (PMID 35501805, 2022).
atherosclerosis (1 paper, 2025). A disease characterized by the build-up of fatty material and calcium deposition in the arterial wall resulting in partial or complete occlusion of the arterial lumen. "In the present study, we focused on the metabolic effect of G0s2 ablation in a mouse model of hypertriglyceridemia and atherosclerosis." (PMID 40100923, 2025). "Despite the protective effects against hypertriglyceridemia, G0s2–/– mice still developed atherosclerosis under atherogenic conditions." (PMID 40100923, 2025). "To evaluate the consequence of G0s2 ablation on diet-induced hyperlipidemia and atherosclerosis, we treated G0s2–/– mice and their WT littermates with the atherogenic Western diet (21.2% fat, 34% sucrose, and 0.2% cholesterol by weight) for 12 weeks." (PMID 40100923, 2025). "Our study highlights the selective role of G0S2 in regulating systemic TG metabolism and its effect on atherosclerosis." (PMID 40100923, 2025).
autoimmune disease (1 paper, 2013). A disorder resulting from loss of function or tissue destruction of an organ or multiple organs, arising from humoral or cellular immune responses of the individual to their own tissue constituents. "Although engineered G0S2 transgenic mice did not exhibit evidence for an autoimmune disease, these mice did have autoimmunity-related antibodies in their serum." (PMID 23546556, 2013).
bladder cancer (1 paper, 2017). "Mechanistically, hnRNPK regulated various functions in bladder cancer by directly mediating cyclin D1, G0/G1 switch 2 (G0S2), XIAP‐associated factor 1, and ERCC excision repair 4, endonuclease catalytic subunit (ERCC4) transcription." (PMID 27862976, 2017).
cardiac hypertrophy (1 paper, 2015). "Recently, it has been observed that there was no change in G0S2 protein content in mouse heart tissue following endurance training-induced cardiac hypertrophy." (PMID 25811590, 2015).
COVID-19 (1 paper, 2022). A disease caused by infection with severe acute respiratory syndrome coronavirus 2. "Neutrophil transcripts which are robustly expressed in the uninfected state, including anti-proliferation and pro-apoptotic genes (LST1, G0S2, CPPED1, BTG2, PMAIP1) and anti-inflammatory genes (AMPD2, SEC14L1, ZFP36), are significantly downregulated in COVID-19 patients." (PMID 36466858, 2022).
cutaneous squamous cell carcinoma (1 paper, 2017). "The aim of this study is to elucidate the methylation status of the CGI located in the 5' region of G0S2 (hereinafter called 5' G0S2 CGI) in cutaneous squamous cell carcinoma (SCC)." (PMID 29073263, 2017).